TOP2A (DNA topoisomerase II alpha)
Diseases named in the same sentence as TOP2A in open-access papers (continued):
Sharing a sentence is not in itself a finding about the gene and the disease.
cancer (continued). "Inhibitors of the DNA topoisomerase 1 (TOP1) and 2 (TOP2A and TOP2B) have shown considerable potential as therapeutic agents against cancers, including HNSCC." (PMID 38920662, 2024). "Our research focused on the diversity within malignant epithelial cells in metastatic ovarian cancer at the individual cell level, revealing the significance of TOP2A and MYBL2 in this type of cancer." (PMID 39136009, 2024). "The most commonly overexpressed genes in rare cancers included BIRC5 (88%), TOP2A (85%), CDK4 (82%), BRIP1 (76%), MSH6 (66%), and HDAC2 (62%)." (PMID 38347552, 2024). "For example, TOP2A, LAG3, SLAMF7, and PTGS2 are established or promising key targets for cancer treatments and immunotherapy." (PMID 38746418, 2024). "Proliferative cancer cells highly expressed proliferation-related genes (MKI67, TOP2A, and TPX2); they also had the highest CytoTRACE score, reflecting strong proliferative potential and higher stemness characteristics." (PMID 37853464, 2023). "Out of these, AURKA, TOP2A, CDK1, and BUB1 were also included in the list of most frequent top NMF genes across the 24 cancer types." (PMID 37973839, 2023). "These drug molecules also showed significant binding performance with some cancer-related PTM-sites (phosphorylation, succinylation, and ubiquitination) of top-ranked four key proteins (EGFR, AURKB, BIRC5, and TOP2A)." (PMID 36567949, 2022). "Thus, TOP2A may be utilized as a specific drug target for malignant tumors such as GC." (PMID 35938042, 2022). "Other known and possibly yet undiscovered cancer mechanisms are captured by the SKY92, including cell cycle pathways (BIRC5, TOP2A, and CENPE), cell growth and proliferation (FGFR3), DNA repair (FANCF, FANCI, POLQ), and transcription factor (STAT1)." (PMID 34448362, 2022). "Then, we validated them by molecular docking analysis with some cancer-related PTM-sites (phosphorylation, succinylation, and ubiquitination) of the four top-ranked key proteins EGFR, AURKB, BIRC5, and TOP2A." (PMID 36567949, 2022). "Survival analysis showed that the CNVs of TOP2B in 13 cancer types, TOP3B in 7 cancer types, TOP2A in 6 cancer types, TOP1MT in 6 cancer types, TOP3A in 5 cancer types and TOP1 in 5 cancer types significantly correlated with overall prognosis." (PMID 36288358, 2022). "TOP2A and KLC1 were the most frequently expressed of the upregulated protein in SaOS mutants, overexpressed in many cancers with TOP2A and expressed in many healthy tissues." (PMID 36010968, 2022). "Based on functions of TOP2A in malignant neoplasm progression and platinum resistance, and HLA-ABC expression in the immune response, the correlation between TOP2A and HLA-I was investigated." (PMID 35784467, 2022). "To investigate the relationship between TOP2A and RRM1 expression and cancer recurrence after treatment with pirarubicin or gemcitabine, we collected 85 NMIBC patient tissues obtained during TURBT." (PMID 35711974, 2022). "Correlation analysis indicated that the mRNA expressions of topoisomerase family genes were positively correlated with their copy number levels in most cancers, such as TOP3A in PAAD and TOP2A in UCEC." (PMID 36288358, 2022). "Like TCTP, a human TOP2 paralog TOP2A is highly overexpressed in cancer cells, and its knockdown suppresses the invasive capacity of the cancer cells." (PMID 34453033, 2021). "Proanthocyanidin b2 and plumbagin were the most common compounds in herbs related to TOP2A and CCNB1, showing good potential for cancer treatment including HCC." (PMID 33946043, 2021). "Paclitaxel was considered a potential drug for cancer therapy due to its inhibition of AURKA and TOP2A." (PMID 34596112, 2021).
cancer (continued). "In this subtype, FOXM1, TOP2A, CCNB1, CCNB2, and CDC25A participate in DNA repair and are activated during disease relapse or play a role in the prognosis of other cancers, thereby supporting the poor prognostic characteristics of the DP.BCG+ subtype." (PMID 33535616, 2021). "Within community 2, we also identified increased expression of regulators of cell proliferation (CENPE, MKI67, TOP2A, UBE2C, guanine), cancer, and pluripotency (DNMT3B, DPPA4, MYC, POU5F1, CRABP2)." (PMID 33771987, 2021). "It is noted that ETOPOSIDE, which targets TOP2A and TOP2B, exists in most drug pairs that are synergistic on the CAOV3 cancer cell line." (PMID 33577560, 2021). "Four studies that measured TOP2A levels within HCC and matched non-carcinoma hepatic tissue samples were identified in the Oncomine database, with a total of 712 samples." (PMID 34939898, 2021). "Positivity of protein marker expression for all cancers combined was: ERCC1 20.9%, MGMT 55.4%, RRM1 19.9%, TOPO1 58.7%, TOP2A 75.8%, TS 34.0% and TUBB3 56.8%." (PMID 31479512, 2020). "Thus, we hypothesize that TOP2A might promote the growth and metastasis of cancer cells." (PMID 32201520, 2020). "Several of them were involved synthetically lethal genetic interactions, especially for RECQL4, TOP2A, MKI67 and ASPM, indicating their potential roles in drug design and cancer treatment." (PMID 32040444, 2020). "To model cancer suppression by these drugs, we generated BRD4- and TOP2A-degron cell lines using the HCT116 CMV-OsTIR1(F74G) background and confirmed the rapid degradation of the fusion proteins." (PMID 33177522, 2020). "Using GEPIA2, a web server integrating TCGA and the GTEx data for 33 cancer types, we found that TOP2A and CENPF expression are higher in tumor than normal tissues in most of cancer types except for LAML, which showed opposite trend for both MRs." (PMID 33023625, 2020). "Meanwhile, we also chose 5 random cancer-related genes for mRNA detection, and found that GADD45A, HBP1, and SESN2 were significantly up-regulated, whereas KIF20A and TOP2A were down-regulated, compared to the 0 h group (*P < 0.05)." (PMID 32850392, 2020). "Increasingly studies have revealed that several genes related to cell cycle such as CDC20, TOP2A, BUBI, BUBIB, and UBE2C, are related to the occurrence and development of cancer, which were also identified in the present study." (PMID 33186389, 2020). "Human cells express TOP2A and TOP2B genes, among which TOP2A is essential for cancer cell division because it is expressed at the S and M phases of the cell cycle, and is required for DNA replication and chromosome segregation for mitosis." (PMID 33598437, 2020). "We also overview the regulation of Top2α by PTM, the level of PTM in cancer cells, and the resistance to therapeutic compounds targeting the Top2 enzyme." (PMID 35582608, 2020). "Our study showed overexpression of TOP2A (log2FC = 3.36) and its upstream regulator FOXM1 indicates that both genes are the promising target for anti-cancer therapy for NSCLC." (PMID 31681566, 2019). "In cancer cells expressing HMGA2, we propose that the protein mitigates the effects of both TOP2 targeting drugs by a combination of DNA supercoil constrainment and TOP2A catalytic activation, hence acting as a DNA supercoil ‘sink’." (PMID 31271486, 2019). "We found that TOP2A, TTK, CHEK1, and CENPA play critical roles in biological processes that are highly correlated with cancer, such as DNA topological structure, cell cycle progression, and mitosis, thereby suggesting their possible role in cancer development." (PMID 30886771, 2019). "In this work, the cancer biomarker ERBB2 and the TOP2α gene showed to be correlated at its copy number." (PMID 31301170, 2019). "Firstly, we used Oncomine database which covers 8603 genes in 203 cancer samples, and we identified TPX2 as the top gene with best correlation with TOP2A, R value = 0.862." (PMID 31528121, 2019).
cancer (continued). "Besides the cell division-associated genes like CCNB2 and BUB1B, we also found genes such as TPX2, BIRC5, TOP2A, SPAG5 and HMGB1, were among the top 10 highly expressed genes in the cell subset, which were reported to be directly or indirectly associated with cancer invasion." (PMID 31888172, 2019). "As USP15 has multiple verified and candidate substrates, it is difficult to assess the relative importance for regulation of TOP2A in USP15 amplified and/or USP15 isoform-1 overexpressing cancer cells." (PMID 29429988, 2018). "To examine the link between MELK and cell division in cancer, we compared the levels of MELK expression with five well-characterized proliferation markers: MKI67, PCNA, CCNB1, MCM2, and TOP2A." (PMID 29417930, 2018). "Most of these genes were expressed across all tumor cells, however, a few cancer genes, including AURKA and TOP2A, were restricted to a minor subpopulation." (PMID 28794488, 2017). "Therefore, our data of increased TOP2A expression and increased sensitivity to doxorubicin in E2 exposed cells further supports the view that higher levels of TOP2A serve as target for doxorubicin and facilitates the increased cytotoxic effects of doxorubicin in cancer cells." (PMID 28323900, 2017). "Here the authors identify TOP2a as substrate for RNF168 and USP10; providing a link between the RNF168/USP10 axis, TOP2a and the response to anti-cancer drugs that target TOP2." (PMID 27558965, 2016). "TOP1, TOP2A and TOP2B levels in several human cancers were reported to be higher than those of normal or benign tissues, which was in accordance to the results from Oncomine." (PMID 27315793, 2016). "For drugs such as etoposide, TOP2A appears to be the most important of the two TOP2 isoforms with regard to induced cytotoxicity and therefore anti-cancer activity." (PMID 22829791, 2012). "Therefore, by targeting TOP2A, NCTD appears to effectively disrupt the cell cycle progression of cancer cells while simultaneously activating tumor suppressor pathways." (PMID 40271060, 2025). "Our study emphasizes TOP2A’s prognostic significance in KIRC and LIHC and recognizes Andrographis paniculata compound as potential therapeutics, offering prospective for enhanced treatment and patient outcomes in these cancers." (PMID 40390492, 2025). "Notably, TOP2A and ZBTB16 are the most frequently upregulated and downregulated ER genes, respectively, across various cancer types." (PMID 41431699, 2025). "This study quantified and validated four cervical precancer and cancer biomarkers—TOP2A, MCM2, VCP, and p16INK4a—in lysates of cultured HeLa, Ca Ski, HT-3, and C-33 A cancer cell lines, as well as normal PCS cells, clinical cervical swab specimens, and cervical tissues." (PMID 40507244, 2025). "Additionally, the data suggest potential new therapeutic targets, such as TOP2A, CDCA7, and STAT1, for future investigations against this aggressive form of cancer." (PMID 40732340, 2025). "The next steps to study the potential of MCPH1 in cancer therapy should address the mapping and characterization of MPCH1 expression levels in several cancer types with different molecular backgrounds and their response to TOP2A catalytic inhibition." (PMID 39885205, 2025). "Abnormal alterations in TOP2A, its interacting proteins, and its modifications may have a critical role in chromosomal instability (CIN) in human cancers." (PMID 41154660, 2025). "YBX1 has predictive value for drug resistance and poor prognosis in more than 20 cancer types, and upregulates the expression of multiple drug resistance genes, including ABCB1, MVP/LRP, TOP2A, CD44, CD49f, BCL2, and MYC, upon UV irradiation or Cisplatin treatment." (PMID 39168971, 2024). "We identified recognized cancer driver genes (EGFR, MTOR, CCND1, and MYC) within Epi_C1_SPARC and Epi_C6_TCIM subclusters, observing high variability of CNVs in cell proliferation-related genes (TOP2A, MKI67)." (PMID 38720887, 2024).
cancer (continued). "We conducted preliminary in vitro and in vivo experiments to confirm that TOP2A, mediating the Hippo-YAP signal pathway, could promote cancer cell growth, metastasis, and osteoclastogenesis in LIHC." (PMID 37980167, 2023). "Collectively, we conclude that TOP2A, mediating the Hippo-YAP signal pathway, could promote cancer cell growth and progression in LIHC." (PMID 37980167, 2023). "The expression of TPX2, TOP2A and MYBL23 was significantly higher in cancer tissues than in paracancerous tissues, but SFTPB was lower in cancer tissues, and that TPX2, TOP2A and MYBL23 high expression groups had poorer OS prognosis, while SFTPB high expression group had better OS (p < 0.05)." (PMID 37407689, 2023). "The first were tightly regulated, through MELK, BRCA2, KIF14, BUB1, and TOP2A, by five TFs (NFE2L3, RUNX1, RUNX2, BHLHE40, and the aging cancer-specific SOX11), two LncRNAs (ST7OT1 and CDKN2BAS), and four miRNAs (miR-21-5p, miR-363-3p, miR-873-5p, and miR-138-1-3p)." (PMID 37191407, 2023). "Enrichment analysis and preliminary in vitro and in vivo experiments confirmed that TOP2A, mediating the Hippo-YAP signal pathway, could promote cancer cell growth, bone-specific metastatic potential and tumor-induced osteolysis in LIHC." (PMID 37980167, 2023). "Notably, we also found a cluster of cells that exhibited higher expression of a set of cell cycle-related genes (CENPF, NUSAP1, PTTG1, STMN1, TOP2A, and TUBA1B), which was consistent with proliferative CAFs (pCAFs) in a previous pan-cancer study of CAFs." (PMID 37833788, 2023). "Gedevo alignments are also related to multiple cell cycle functions, and some of them show evidence of dysregulation in cancer (ASPM, CENPF, TOP2A, and TPX2) and the acquisition of two hallmarks of cancer: sustaining proliferative signaling and evading apoptosis." (PMID 36661515, 2023). "Notably, as co-expressed genes, TOP2A, BUB1 and CENPE also interacted with the CENPF protein, the high expression of which predicted poor prognosis in cancers." (PMID 37108172, 2023). "Knockdown of TOP2A and CDC45 has been shown to suppress the growth of various cancer cells." (PMID 36142506, 2022). "Similarly, a 4-gene (TOP2A, SLC22A1, PDZK1IP1, RDH16) combination for predicting cancer recurrence was selected." (PMID 35422802, 2022). "Although there have been numerous studies focusing on TOP2A’s oncogenic role and regulatory networks in tumors, we found that there was no comprehensive systematic analysis of TOP2A from the pan-cancer aspect available." (PMID 35778520, 2022). "There are highly mitotic/proliferative clusters (TOP2A, MKI67) of both LUAD and LUSC that may resemble highly aggressive and invasive cancer cells." (PMID 36368318, 2022). "A characteristic of cancer cells is increased or otherwise altered PTMs modulating enzyme activity, and Top2α is no exception." (PMID 34532656, 2021).
cancer (continued). "Specifically, ANLN, ARNTL2, TOP2A, PLAU, and VCAN expression are important in the invasion of the basement membrane, intravasation, extravasation, and colonization at secondary sites, but only TOP2A and ARNTL2 contribute to the survival of cancer cells while in circulation." (PMID 34591244, 2021). "A clear trend toward differential RFS and OS benefit with anthracycline-based therapy in TOP2A amplified (ratio >2) cancers was noted but did not meet statistical significance." (PMID 34625570, 2021). "We found that the two synergistic MRs TOP2A and CENPF have both the high magnitude of increase of expression (vs. normal tissue) and the high absolute expression level in CC compared to many other cancer types." (PMID 33023625, 2020). "To explore more related to drug selection in clinical use for cancer patient, we queried CMap database using CLUE and identified potential perturbations that could reverse the over-expression signature of TOP2A, CENPF and their common regulons." (PMID 33023625, 2020). "The majority of phosphorylations were identified in the Top2α CTD in normal and cancer cells." (PMID 35582608, 2020). "Notably, the transcription factor MYBL2 is a central regulator of cell survival, proliferation and differentiation in cancer, and PLK1 and TOP2A are druggable by clinically advanced inhibitors." (PMID 32824422, 2020). "Meanwhile, no significance relationship was found between TOP2A expression and patients race, age and cancer stage." (PMID 31528121, 2019). "Using bioinformatic analysis, we revealed that TOP2A could be adopted as a prognostic indicator of NSCLC and it potentially regulate cancer development through co-work with TPX2." (PMID 31528121, 2019). "The result revealed that both TOP2A and TPX2 expressed much higher in cancers (both LUAD and LUSC) comparing to normal lung tissues, and Pearson correlation analysis results showed that TOP2A expression was highly similar to TPX2, R = 0.59, 0.79 in LUAD and LUSC respectively." (PMID 31528121, 2019). "Besides, regarding with the relationship between anticancer drugs and hub genes, TOP2A and RRM2 were the targets of cancer drugs in patients with OC." (PMID 31729978, 2019). "B Cancer specific survival, progression free survival and recurrence free survival curve between TOP2A high and low expression patients with non-muscle invasive bladder cancer (NMIBC) patients (n=79)." (PMID 31216997, 2019). "TOP2A is thus known to be a marker of cell proliferation in normal tissue, and increased TOP2A expression levels are observed in cancer cells compared with non-malignant cells." (PMID 31216997, 2019). "Top2β, but not Top2α, appears to play a main role in the increased cancer incidence in patient survivors." (PMID 30404148, 2018). "Furthermore, AREG affected downstream molecules like BIRC5, CCNA2, CCNB2, TOP2A, MMP9, MMP1, CXCR4, have roles in development and progression of various types of cancers." (PMID 30517191, 2018). "Top2α-DOX-DNA complex inhibits DNA replication and chromosome condensation/decondensation, and arrests the cell cycle in G1/G2, thereby inducing apoptosis in proliferating cancer cells." (PMID 30483123, 2018). "TOP2A (DNA topoisomerase 2-α) and RRM2 (ribonucleoside-diphosphate reductase subunit M2) are noteworthy examples of proteins with both a well-established role in cancer development and prognostic value." (PMID 26527623, 2016). "The resistant cell lines were analyzed for cross-resistance to other anti-cancer drugs, global gene expression, growth rates, TOP1 and TOP2A gene copy numbers and protein expression, and inhibition of the breast cancer resistance protein (ABCG2/BCRP) drug efflux pump." (PMID 26801902, 2016). "The TOP2 poison, doxorubicin, functions by arresting TOP2A in cleavable complexes, resulting in double-strand DNA breaks and subsequent apoptotic cell death of cancer cells." (PMID 27557643, 2016).